AMY2A (amylase alpha 2A)
Synonyms: PA; AMY2
Tractability: Small molecule: a structure with a bound ligand is known; a high-quality ligand is known; it has a binding pocket of medium quality; it belongs to a druggable protein family. Antibody: its Gene Ontology location is reachable by antibodies, with high confidence; UniProt places it where antibodies can reach, with medium confidence; UniProt predicts a signal peptide or a membrane-spanning region. PROTAC: a small molecule that binds it is known. Other modalities: an approved drug acts on it.
Target class: Enzyme; Hydrolase
Gene: Protein-coding gene on chromosome 1 (103,617,427 to 103,625,780, forward strand). Ensembl gene ENSG00000243480.
Subcellular location: Secreted, extracellular space
Subcellular location (Human Protein Atlas): Cytosol; Golgi apparatus; Predicted to be secreted
Pathways (Reactome):
Developmental Biology: Developmental Lineage of Pancreatic Acinar Cells
Digestion and absorption: Digestion of dietary carbohydrate
Gene Ontology:
Molecular function: alpha-amylase activity; calcium ion binding; chloride ion binding; catalytic activity; cation binding
Biological process: carbohydrate catabolic process; carbohydrate metabolic process; polysaccharide digestion
Cellular component: extracellular exosome; extracellular region
Genetic constraint (gnomAD): Loss-of-function variants: 12 observed, 22.94 expected, observed/expected ratio (o/e) 0.52, 90% interval 0.33 to 0.85. The synonymous counts are far from expectation, so gnomAD's model fits this gene poorly and the ratio says little. Missense variants: 140 observed, 217.99 expected, observed/expected ratio (o/e) 0.64, 90% interval 0.56 to 0.74. Synonymous variants: 46 observed, 66.48 expected, observed/expected ratio (o/e) 0.69, 90% interval 0.55 to 0.88.
Homologues: Orthologues: chimpanzee AMY2A (98% identical), macaque AMY2B (96% identical), tropical clawed frog amy2a (77% identical), tropical clawed frog amy2b (75% identical), Drosophila melanogaster Amy-p (52% identical), Drosophila melanogaster Amy-d (52% identical), Drosophila melanogaster Amyrel (47% identical), Caenorhabditis elegans C50B6.7 (47% identical), Drosophila melanogaster Mal-A7 (15% identical), Drosophila melanogaster Mal-A4 (15% identical), Drosophila melanogaster Mal-B2 (14% identical), Drosophila melanogaster Mal-A8 (14% identical), and 4 more. Paralogues in human: AMY2B (99% identical), AMY1A (97% identical), AMY1B (97% identical), AMY1C (97% identical), SLC3A1 (18% identical), GBE1 (15% identical), SLC3A2 (13% identical).
Diseases named in the same sentence as AMY2A in open-access papers:
AMY2A is named in the same sentence as 22 diseases in open-access papers, as found by Europe PMC text mining. Sharing a sentence is not in itself a finding about the gene and the disease. The quoted sentences say what the papers report.
diabetes (2 papers, 2022). "Using the predefined threshold (p = 0.05), we confirmed the statistically significant association of AMY1 and AMY2A CNs with diabetes and HbA1c." (PMID 35538098, 2022). "In this study, we aimed to investigate the fundamental relationships of AMY1 and AMY2A with diabetes and obesity in a homogenous northern Japanese population considered to have a high starch intake." (PMID 35538098, 2022).
gastric carcinoma (2 papers, 2014 to 2015). A carcinoma that arises from epithelial cells of the stomach. "A homozygous deletion of the AMY2A gene is possibly involved in the pathogenesis of gastric carcinoma." (PMID 24743780, 2014). "AMY2A gene may have potential for tumor suppression in gastric carcinoma." (PMID 24743780, 2014).
pancreatic cancer (2 papers, 2019 to 2024). "Pancreatic alpha-amylase (AMY2A) has been related to cell adhesion, growth, and the invasion of cancer cells and it has been proposed as a candidate urine biomarker for pancreatic cancer." (PMID 30813269, 2019).
COVID-19 (1 paper, 2024). A disease caused by infection with severe acute respiratory syndrome coronavirus 2. "Evidently, the levels of AMY2A and AMY2B were relatively higher in survivors of COVID-19 compared to those who died of COVID-19." (PMID 38575325, 2024).
Hyperglycemia (1 paper, 2023). An increased concentration of glucose in the blood. "The laminins LAMA2 and LAMB4 are targets in the treatment of ocriplasmin vitreomacular adhesion, whereas the amylases AMY2A and MGAM are targeted by acarbose, voglibose and miglitol for the improvement of postprandial hyperglycemia." (PMID 37684227, 2023).
systemic lupus erythematosus (1 paper, 2015). An autoimmune multi-organ disease typically associated with vasculopathy and autoantibody production. "Meanwhile, the CNV-driven genes were significantly enriched in pathways of systemic lupus erythematosus, starch and sucrose metabolism pathway (amylase alpha 2A, AMY2A)." (PMID 26297502, 2015). "For example, FCGR3A, FCGR2B and HLA-DQA1 may function via the systemic lupus erythematosus pathway, and AMY2B and AMY2A may participate in lung SCC via starch and sucrose metabolism pathway." (PMID 26297502, 2015).
tumor (2 papers, 2014 to 2017). "Mohammad showed that gene losses of AMY2A, TGFA, and REG1B in uterine leiomyosarcoma may be responsible for secondary changes that affect the progression and proliferation of the tumor." (PMID 24743780, 2014).
AMY2A also shares sentences with these, for which no sentence is quoted: cancer (3 papers); autoimmune pancreatitis (2); pancreatitis (2); adenocarcinoma (1); autoimmune hemolytic anemia (1); cognitive decline (1); herpesvirus infections (1); kidney disease (1); lentivirus infection (1); lipomatosis (1); lung carcinoma (1); memory impairment (1); pancreatic insufficiency (1); schizophrenia (1); vitiligo (1).